MYC (MYC proto-oncogene, bHLH transcription factor)
Diseases named in the same sentence as MYC in open-access papers (continued):
Sharing a sentence is not in itself a finding about the gene and the disease.
tumor (continued). "The results showed that EC-targeted delivery of miR-218 significantly downregulated MYC expression, accompanied by repressed TEC proliferation, although tumor growth was not obviously changed." (PMID 40303332, 2025). "In tumours without PMN-alterations but with MYC-overexpression, genes correlated with MYC-overexpression were identified." (PMID 38877600, 2024). "Tumor immune microenvironment analysis and GSEA results showed that the activation of MYC targets genes rather than immunosuppression contribute to the poor survival outcome of patients in the high-risk group." (PMID 39538125, 2024). "On the contrary, CM-272 increased levels of genes related to tumor growth suppression: CPA4 (Carboxypeptidase A4), a negative regulator of the AKT/c-MYC pathway in NSCLC and GNG2 (G-protein gamma subunit 2), which impairs AKT phosphorylation and cell survival." (PMID 39488528, 2024). "Within the subset of tumours without PMN-hits (PMN-WT cases, n = 86) we examined genes whose expression levels were correlated with MYC expression." (PMID 38877600, 2024). "The KLF6, MYC, and FOSL2 genes did not seem to follow the EGR1/FOS expression pattern in the analyzed tumor samples." (PMID 39436655, 2024). "A recent study has also shown that although MAX inactivation can accelerate SCLC progression, this effect is independent of MYC, and MAX deletion in MYC-overexpressing SCLC also leads to tumor abrogation." (PMID 38992040, 2024). "The combination of castration and Mediator kinase inhibition downregulated the MYC pathway, and Mediator kinase inhibition suppressed a MYC-driven CRPC tumor model even without castration." (PMID 38546787, 2024). "For MYC the median copy number was 2.10 (IQR 1.94–2.38) in tumor tissues and 1.96 (IQR 1.89–2.03) in non-tumor tissues and the difference between tumor and non-tumor was statistically significant (p < 0.0001)." (PMID 37858127, 2023). "Analysis of DNA from Patient 3’s tumor did not reveal a copy number alteration of c-MYC, yet we observed elevated c-MYC expression in a liver biopsy taken prior to the observation of intrinsic T/HCQ resistance." (PMID 36719686, 2023). "Conversely, MYC and MYCN genes display very low correlation and show only a very modest induction in the BRAF- (vs RAS-like) tumour subgroup and are not differentially expressed in tumours vs healthy samples’ comparison." (PMID 37198319, 2023). "Consistently, ectopic expression of MYC and PIK3CAE545K with and without MEK1DD or ER-KRASG12V enhances clonogenic potential of the late-passage HCK1T/16epi cells and hence tumor-forming ability." (PMID 36763589, 2023). "Tumours that are predominantly positive for MYC are in either POU2F3 or YAP1 subgroups, while MYC negative tumours are mostly in ASCL1 and NEUROD1 subtypes." (PMID 37870696, 2023). "If Onalespib treatment requires presence of ARF and MYC, rather than MYCN, for successful tumor cell inhibition, it would be expected that D283 and D425 cells would be more sensitive to HSP90 inhibition than DAOY cells." (PMID 36869047, 2023).
tumor (continued). "Therefore, targeting MYC-regulated miRNAs appears to represent a suitable strategy to interfere with MYC-dependent cancers, although it may be difficult to deliver miRNA mimetics into the tumor tissue of interest without losing their efficacy due to premature degradation." (PMID 36969025, 2023). "Overall confirming that presence of ARF expression, as well as MYC, but not MYCN, are key identifiers of successful tumor cell response and ablation to HSP90 inhibition in both our animal models and in human lines." (PMID 36869047, 2023). "Therefore overexpression of MGA, caused by (P)RR knockdown, could disturb this balance, limiting the supply of MAX for MYC heterodimerization and antagonizing MYC-dependent cell processes; re-routing the tumour cell from a proliferative to a non-proliferative state." (PMID 35401936, 2022). "CTC CNAs, including amplifications of MYC, BCL6, DDR2, SOX2 and deletions of CDKN2A/B, were more likely to be shared with residual rather than primary tumor." (PMID 35087134, 2022). "Our study showed a significant positive correlation between cell proliferation rate as well as tumor stemness and MYC score, and further highlights its non-negligible role in regulating LUAD cell proliferation and maintaining tumor stemness." (PMID 36299592, 2022). "Immunohistochemistry revealed that tumor cells were positive for CD20, BLC6, BLC2, and c-MYC and negative for CD10, MUM1, and CD5." (PMID 35334633, 2022). "Other copy number reduced genes included SMAD4, HNF1B, and some gene loci that are not known to be tumor suppressor genes, such as KRAS, MYC, PIK3CA, and IL6." (PMID 36430324, 2022). "For 54 cases without additional HR characteristics (residual tumor > 1.5cm2, LCAMB, MYC amplification, MYCN amplification in other subgroups than Group 4), full molecular information was available for 22/45 patients ≥ 4 years and all nine patients < 4 years." (PMID 35190934, 2022). "On the contrary, should we target the MYC-MAX complex, we would have success in all the cases but in 2 RMS and in 1 WT in which MAX is not expressed in all the samples of the tumor mass." (PMID 36284197, 2022). "However, as mentioned in the Introduction, it is important to distinguish between MYC’s role as a primary driver oncogene versus that of a tumor facilitator that simply provides metabolic and/or translational support without being necessary for tumor initiation." (PMID 35203395, 2022). "Notably, among the five major NKG2DL, MICB was the main NKG2DL regulated by MYC in H2227 cells, while MICA was the main one regulated by MYC in H446 cells, indicating that the regulatory pathways of the same NKG2DL may be different in distinct tumor cells, which required to be further studied." (PMID 35158730, 2022). "Irrespective of oncogenic driver, tumour cells upregulate USP28, which stabilizes proto‐oncogenes, such as c‐MYC, c‐JUN or NOTCH." (PMID 35364627, 2022). "Given the recently discovered role of MYC in driving the temporal evolution of SCLC from NE to non-NE fate, we sought to estimate the intratumor heterogeneity in terms of MYC-driven tumor progression." (PMID 35440132, 2022). "Low proliferative, but not high proliferative, luminal tumours also showed a weak positive correlation between GLS2 protein and c-MYC (p < 0.001), SLC1A5 (p < 0.05) and SLC3A2 (p < 0.001)." (PMID 34439127, 2021). "In the study, gain of MYC or the PVT1/CCDC26/GSDMC region alone did not result in tumourigenesis, but co-amplification of MYC and PVT1/CCDC26/GSDMC resulted in a pro-tumour transformation." (PMID 33499210, 2021). "In the first, tumor was considered present if any tumor marker (hTERT n=7; TERC/GAPDH>3.12 n=6, MYC/GAPDH>0.155 n=7) was present with or without HPV positivity and tumor absent if all tumor markers were absent regardless of the presence or not of HPV." (PMID 34790573, 2021). "GW5074 was not as effective in modulating the tumor infiltration of total CD3+ lymphocytes or tumor progression and maintained MYC expression." (PMID 34947972, 2021).
tumor (continued). "A FISH study of tumor tissue in this case revealed additional signal at the c‐MYC/8q24 gene locus and the lack of c‐MYC/8q24 rearrangements." (PMID 32100426, 2020). "Although we did not observe a significant difference in MYC (p = 0.08) or LPL (p = 0.11) expression between basal-TNBC and CL-TNBC, we did find that CL-TNBC tumours had significantly higher expression of CD36 (p < 0.0001) and PDGFRB (p < 0.0001)." (PMID 31942031, 2020). "The tumor inhibition and extended survival were attributed to increased infiltration of CD3+CD4+CD44+ immune cells and not suppression of MYC." (PMID 33178203, 2020). "In contrast, neither BMN673 nor JQ1, alone or in combination, inhibited tumor growth in H196 xenografts, which indicated that combined BMN673-JQ1 treatment was not effective against MYC paralog-independent SCLC in vivo." (PMID 33134168, 2020). "While we did not observe a substantial additive effect on tumor growth inhibition when DHE and JQ1 were combined, this supports the idea that both drugs converge on the same molecular target, namely the MYC SE." (PMID 32071334, 2020). "Most MYC target genes are regulated in a dose dependent manner and non-MYCN-amplified tumor cells that artificially overexpress MYCN retain their ability of neuronal differentiation." (PMID 33585251, 2020). "Upon treatment of these tumours with anti-RSPO3 antibody using patient-derived xenograft models, expression of LGR5 and ASCL2 were highly downregulated, whereas MYC, AXIN2 and CCND1 (cyclin D1) did not rank among the top 100 downregulated genes." (PMID 30792270, 2019). "In tumor tissues from HCC-B patients, a significantly higher level of c-MYC was recruited to the E-box than in non-tumor tissues." (PMID 31739577, 2019). "PKM2, but not PKM1, is selectively expressed in proliferating or tumor cells, and can disassociate HDAC3 from the MYC promoter to promote GBM tumorigenesis through directly binding and phosphorylating histone H3." (PMID 31450721, 2019). "Strikingly, tumor development in LMP2A/λ-MYC/p27Super mice was later than that in λ-MYC mice and not significantly different from that in λ-MYC/p27Super mice." (PMID 30992353, 2019). "While the absence of TET2 in MYC-driven tumors does not automatically mean it reinforces the tumor state, our ectopic TET2 expression experiments indicate a role as tumor suppressor." (PMID 31266538, 2019). "TcR-sequencing revealed a polyclonal repertoire of tumor cells indicating that co-expression of MYC, activated AKT and BCLXL is sufficient for tumor transformation and do not require acquisition of additional genetic events." (PMID 29765548, 2018). "These tumor cells did, however, not respond to CDK9 inhibition when we used the highly specific CDK9 inhibitor LDC000067, previously reported to target MYC." (PMID 29511348, 2018). "We are first to report that in PTSMTs, a non-canonical activation of WNT, independent of beta-catenin, drives tumor cell proliferation via MTOR/AKT1, MYC and Cyclin D2." (PMID 29881541, 2018). "The results of additional immunohistochemical studies (BCL2, MYC, Ki67) showed no impact on CD52 expression status, and tumor morphology (blastoid vs. DLBCL vs. DLBCL/BL) was similarly non-predictive." (PMID 30020951, 2018). "We found that an anti-miR-17 LNP, in a transgenic mouse model of MYC-driven HCC, impeded tumor progression without overt signs of hepatic or systemic toxicity." (PMID 29464015, 2018).
tumor (continued). "The tumor showed positive immunostaining for Vimentin, CD31, CK7, D2–40, c-MYC, Ki67, focal positivity for PanCK, and negative immunostaining for Factor VIII, CD34, WT1, CK5/6, Calretinin, EMA, HBME-1, CEA, p63, EpCAM, Bcl-2, TTF1 and Thyroglobulin." (PMID 28810922, 2017). "Treatment with CCl4 alone did not induce tumorigenesis, but promoted c-MYC and shp53-induced HCC, leading to tumor development within three months of treatment." (PMID 28422055, 2017). "However, co-culture with PrSC did not induce the expression of MYC in these cells, suggesting that elevated MYC in NHPrE1/AR tissue recombinants may result from the presence of other cellular components in the tumor microenvironment." (PMID 27611945, 2016). "In the tumor initiation, the opposite role of YWHAE and CDC25B in gastric carcinogenesis seems to be independent of MYC expression." (PMID 27863420, 2016). "No clinicopathologic features were significantly different between DLBCL patients with concurrent MYC/BCL6 rearrangements versus patients without MYC/BCL6 concurrent rearrangement, although larger tumor size was of borderline significance (P = 0.058)." (PMID 26573234, 2016). "The results show that U2OS cells express levels of MYC that are comparable to non-transformed cells (IMEC, HMLE, MCF10A) and lower than those found in other tumor cell lines (HeLa and HCT116)." (PMID 27460974, 2016). "In GC samples from a Chinese population, a correlation between MYC and CDC25B immunoreactivity was described; however, the effect of tumor stage in the immunoreactivity of these proteins was not accessed." (PMID 27863420, 2016). "Here, comparison of tumor and surrounding normal tissue verified MYCN, but not c-MYC mRNA expression in three of the nine tumors analysed, while neither MYCN nor c-MYC amplifications were detectable." (PMID 27769070, 2016). "In tumor xenografts of SULT2B1-RNAi-LV cells, cyclinB1, MYC and BCL2 protein levels decreased, while no significantly differences in cyclinD1 protein levels was observed between the two groups." (PMID 23593328, 2013). "The mRNA levels for several critical components of the pathway (BIRC5, CD44, FZD7, c-MET, MMP7, c-MYC, NOTCH1, PPARD, and VEGF) were significantly increased (DASL signal intensity) in TN tumor samples as compared to non-TN tumor samples." (PMID 24143235, 2013). "When the tumor subtypes without a counterpart were analyzed via GSAA, we observed PDGFRB_STP co-expressed with aberrantly expressed MYC and STAT3 only in luminal A." (PMID 23516564, 2013). "Note that in the absence of tumor formation at day 3, the expression of PPAT, IMPDH1, IMPDH2, DHODH but not PAICS are all statistically significantly elevated with MYC induction." (PMID 18628958, 2008). "We were able to detect HEL transcripts and HEL protein in cells obtained from either a primary Eμ-MYC/BCRHEL/sHEL tumor or an MMTV-TRE-MYC/BCRHEL/sHEL tumor, but not in cells obtained from either Eμ-MYC or Eμ-MYC/BCRHEL tumors (unpublished data)." (PMID 18578569, 2008). "Conversely, MYC levels do not change, or are reduced in the NTG contingent of tumor cells, which themselves are progeny of CoCSC." (PMID 18560594, 2008). "In contrast to previous studies, gains of 8q24.1 (MYC) and 17q12 (HER2) were not significantly more frequent in ER-positive tumours." (PMID 17133270, 2007). "We quantitated MYC in twelve available tumor specimens with qRT-RTPCR and found that MYC was not significantly upregulated in the two tumors with 8q gain (t = 0.49)." (PMID 16968546, 2006). "IHC analysis of a subcutaneous tumor also revealed that a MYC‐overexpressing tumor highly exhibited MP markers, including markers of EMT, cell adhesion, and resistance to shear stress, but this which was not solely attributed to tumor volume." (PMID 39899538, 2025).
tumor (continued). "The histopathologic subtype of DLBCL in this patient is the non-GCB subtype with MYC/BCL-2 dual expression and a high Ki-67 proliferative index, consistent with a biologically proliferative tumour, which is reflected in the clinical presentation of acute splenomegaly with splenic infarcts." (PMID 41306146, 2025). "Our analysis across tumor types showed that MYC amplification occurred without amplification of HSF1 in a lower percentage of patients, whereas HSF1 was also amplified without MYC amplification." (PMID 39831777, 2025). "Notably, the protein expression patterns helped to differentiate non-malignant proliferative cells from tumor-derived models, most clearly through the selective upregulation of HMGCL in HepaFH3 cells and c-MYC in HCLs." (PMID 40862732, 2025). "Supporting this interpretation, GPC3 and c-MYC showed parallel upregulation in HCLs but not in HepaFH3 or PHHs, consistent with reports that c-MYC can transcriptionally upregulate GPC3 expression, reinforcing their potential combined value as tumor biomarkers." (PMID 40862732, 2025). "However, MYC expression was not significantly reduced in HeLa and CE81T cell‐derived tumours, even in those with downregulated glycolysis and PPP." (PMID 40186514, 2025). "Therefore, MYC and MYCN are probably not the primary ‘drivers’, but instead are acquired after malignant transformation and probably accelerate tumour growth." (PMID 40335697, 2025). "However, the negative correlation between MYC and SLC1A5 expression was significant only for luminal A tumours (P = 0.01) and not for the other subtypes (P > 0.05)." (PMID 39843491, 2025). "However, despite the preclinical demonstration that inhibiting MYC and RAS can be sufficient to induce sustained tumor regression, no drugs that directly target these oncogenes made it to the clinic until recently." (PMID 39164274, 2024). "In BCPAP cells treated for 72 h, genes from the canonical Wnt pathway (FZD1, DVL1, AKT2, CTNNB1, LEF1, MYC) and the non-canonical Wnt pathway (RHOA, related to cytoskeletal dynamics and increased migration and invasion) were upregulated, suggesting pro-tumor behavior." (PMID 39125748, 2024). "Given the roles of NOTCH and MYC in SCLC NE to non-NE plasticity, it is notable that NOTCH, MYC, and hypoxia signaling are also entwined in regulating endothelial angiogenesis, suggesting that they are key factors in tumor-endothelial differentiation in SCLC." (PMID 37455012, 2023). "HCK1T/16epi with expression of both MYC/PIK3CAE545K and MEK1DD resulted rapid tumor formation regardless of the early-passage or the late-passage; tumor volumes reached more than 600 mm3 in all mice (100%; 4 of 4 for each passage) within 4 weeks for early-passage and 3 weeks for late-passage cells." (PMID 36763589, 2023). "This study found that mice injected with the anti-CD19 CAR EVs loaded with MYC-CRISPR had slowed tumor growth compared with those injected with MYC-CRISPR-loaded EVs without CAR modifications, and the tumor cell damage was observed in immunohistochemical studies." (PMID 38138963, 2023). "Because the IG::MYC rearrangements were easily identified in tumor WGS but not in peripheral blood, this reduces the concern about false-positive mCAs detection due to contamination of peripheral blood DNA by tumor cells." (PMID 38057307, 2023). "In accordance with the finding that MYC S146L may induce context dependent OIS or apoptosis in non-transformed epithelial cells, this substitution likely evolves later in tumor evolution, rather than as a primary initiating event." (PMID 36018850, 2022). "In addition, Oxy186, but not Oxy210, also inhibits A549 xenograft tumor growth in vivo, and RNA-seq analysis of Oxy186-treated xenograft tumor samples confirmed the inhibition of WNT target gene expression, including MYC and Cyclin D1 (CCND1)." (PMID 35908024, 2022).